EBF3 (EBF transcription factor 3)
Diseases named in the same sentence as EBF3 in open-access papers (continued):
Sharing a sentence is not in itself a finding about the gene and the disease.
tumor (continued). "As expected, double immunostain combining GFAP and EBF3 showed a selective EBF3 expression in the GFAP-negative MB tumor component, suggesting co-existence of two different major tumor subclones with either glial or early neuronal differentiation." (PMID 36941703, 2023). "Immunohistochemical analysis of this tumor showed a mutually exclusive expression of ARR3 and EBF3, defining two types of areas (CRX+/ARR3+/EBF3− and CRX+/ARR3−/EBF3+), as observed in about 30% of subtype 2 tumors." (PMID 34552068, 2021). "In the present study, we have investigated DNA methylation changes in EBF3 and TBC1D16 in publicly available data of multiple different tumour types, so as to further evaluate the potential role of these two genes associated with tumourigenesis and metastasis." (PMID 31383000, 2019). "The remaining three common genes (EBF3, DKFZp667I0324 and RBMS1) were all bivalent in normal tissue but lost all their histone methylation in tumor." (PMID 22011431, 2011). "Additionally, several tumor suppressor genes involved in tumor growth metastatic invasion, such as CTNNAI, IKZFI, or EBF3, can be identified as new targets of miR-197." (PMID 36143221, 2022). "The co-expression of CRX/EBF3/GAP43 (early photoreceptor/cone marker and neuronal/ganglion cell markers) was unique to tumor cells as it was absent or very rare during normal retinal development." (PMID 34552068, 2021). "However, epigenetic changes in EBF3, or TBC1D16, were not identified in all tumour samples, or in all primary/metastasis cancer pairs." (PMID 31383000, 2019).
cancer (7 papers, 2015 to 2024). A tumor composed of atypical neoplastic, often pleomorphic cells that invade other tissues. "The early B-cell factors (EBFs) are transcription factors with EBF3 playing dual oncogenic roles, depending on the cancer type, and linked to poor outcomes in various cancers." (PMID 39139281, 2024). "This project also provides a platform for investigating the causative role of epigenetic drivers in cancer metastasis, both with respect to establishing optimised techniques for targeted methylation investigation and through providing insight into the role of EBF3 in metastasis." (PMID 38473261, 2024). "Using subsequent gene expression analysis, we provide novel clues about the function of EBF3 in cancer cells." (PMID 38473261, 2024). "In the remaining primary cancer cell lines, the EBF3 promoter was either hypermethylated or exhibited an increase in methylation compared to normal, whereas the gene body CpG sites were almost fully unmethylated." (PMID 31383000, 2019). "MAPRE3 (also known as EB3 or EBF3) codes for a microtubule end-binding protein that stabilizes focal adhesions and has been demonstrated to trigger apoptosis in cancer types other than those analyzed here." (PMID 28423600, 2017). "As such, EBF3 influences the accessibility of target genes and plays a role in shaping the transcriptional landscape in various cellular processes, including development, differentiation, and disease, such as cancer." (PMID 38473261, 2024). "For example, it appears that the EBF3 promoter hypermethylation identified by RRBS may potentially be an early universal marker for detecting the presence of several cancer types, which have undergone aberrant methylation." (PMID 31383000, 2019). "Hypermethylation of the EBF3 promoter (at a region between +700 and +1030 downstream from the transcription start) and down-regulation of EBF3 expression in contrast to up-regulation, as observed in our study, has been reported in several cancers." (PMID 28030832, 2017). "Therefore, H3K27Me3 might be involved in preserving the undifferentiated state of cancer stem cells (CSCs) through the repression of differentiation-related genes like EBF3." (PMID 38473261, 2024). "Nevertheless, evaluation of both EBF3 promoter and gene body in WGBS data enabled us to examine the exact same CpG sites in normal and cancer tissues and cell lines, and the methylation changes were consistent with previously published data." (PMID 31383000, 2019). "Overall, the findings presented strengthen the view that methylation changes in EBF3 and TBC1D16 are potential epi-drivers of aggressive tumourigenic changes in multiple cancer types." (PMID 31383000, 2019).
neurodevelopmental disorder (7 papers, 2017 to 2025). A behavioral and cognitive disorder with onset during the developmental period that involves impaired or aberrant development of intellectual, motor, or social functions. "In this study, we follow up on our previous identification of variants in individuals with neurodevelopmental disorders in the enhancer hs737 that affects the target gene, EBF3." (PMID 41081394, 2025). "The first neurodevelopmental disorder risk gene we assessed was EBF3•unc-3, which is a highly conserved transcription factor." (PMID 35363276, 2022). "Variants in EBF3 have been associated with multiple neurodevelopmental disorders including ASD and ID, and are thought to confer risk through haploinsufficiency or by interfering with DNA binding." (PMID 35363276, 2022). "The EBF3 gene encodes a transcription factor that preferentially binds to the promoters of other transcription factors and chromatin-binding proteins involved in neurodevelopmental disorders (NDDs) (e.g. CHD2, CHD8, ARID1B)." (PMID 41081394, 2025). "EBF3 is well-established as a syndromic gene and has genome-wide significance for excess variation in individuals with neurodevelopmental disorders." (PMID 41081394, 2025). "Protein-coding DNVs of EBF3 are also known to be genome-wide significant for excess in neurodevelopmental disorders." (PMID 41081394, 2025). "This mouse model provides a useful tool to others in the field especially those studying the EBF3 gene regulatory network (GRN) that has been implicated in autism and other neurodevelopmental disorders." (PMID 41081394, 2025). "This work provides critical insights into coding and noncoding DNVs at EBF3 and more generally in neurodevelopmental disorders." (PMID 34256850, 2021). "Further, we observed an excess of deletions of hs737 in individuals with neurodevelopmental disorders consistent with the finding that both EBF3 and its associated regulatory elements are required for normal neural development." (PMID 41081394, 2025).
EBF3 also shares sentences with these, for which no sentence is quoted: hypotonia, ataxia, and delayed development syndrome (5 papers); Hypotonia (4); Strabismus (3); adenocarcinoma of the lung (1); breast invasive carcinoma (1); cerebellar ataxia (1); cholangiocarcinoma (1); colon adenocarcinoma (1); cryptorchidism (1); Dysarthria (1); Dyskinesia (1); Dystonia (1); familial melanoma (1); hemangioma (1); hyperplastic (1); intrauterine growth restriction (1); Koolen-de Vries syndrome (1); lung squamous cell carcinoma (1); medulloblastoma (1); microcephaly (1); Micropenis (1); nasopharyngeal carcinoma (1); neurological disorders (1); ocular melanoma (1); rectum adenocarcinoma (1); Shashi-Pena syndrome (1); small cell lung carcinoma (1); stomach adenocarcinoma (1); Tracheomalacia (1); Tremor (1).
A further 5 diseases each share a sentence with EBF3 in 1 paper.